MTOR (mechanistic target of rapamycin kinase)
Diseases named in the same sentence as MTOR in open-access papers (continued):
Sharing a sentence is not in itself a finding about the gene and the disease.
esophageal squamous cell carcinoma (continued). "Ulk1, which plays an essential role in autophagosome formation through activation or regulation of the AMP activated protein kinase and mTOR, is overexpressed in esophagus squamous cell carcinoma." (PMID 23593401, 2013). "Additionally, miR-100 inhibited cell proliferation by suppressing mTOR in esophageal squamous cell carcinoma (ESCC) cell lines and Low miR-100 expression was associated with worse overall survival in ESCC patients." (PMID 23978303, 2013). "In addition, METTL1-mediated tRNA m7G modifications promote the translation of mTOR pathway components, thereby facilitating mTOR activation and progression of esophageal squamous cell carcinoma." (PMID 40443650, 2025). "GA-D downregulates the expression of phosphorylated proteins in the mTOR signaling pathway, including PI3K, AKT, and mTOR, thereby synergistically promoting apoptosis and autophagic cell death in esophageal squamous cell carcinoma cells, achieving effective adjuvant anti-cancer activity." (PMID 39459639, 2024). "Additionally, UHRF1’s regulation of the PI3K/Akt/mTOR pathway in esophageal squamous cell carcinoma further illustrates the extensive impact of these proteins on cancer pathophysiology, offering novel insights into potential therapeutic targets." (PMID 38813086, 2024). "Similarly, PHD-containing protein UHRF1 regulates esophageal squamous cell carcinoma via the PI3K/Akt/mTOR pathway, facilitated by the demethylation of tumor suppressor genes." (PMID 38813086, 2024). "Moreover, FADS1, which catalyzes DGLA to AA, was also increasingly expressed in esophageal squamous cell carcinoma and regulated cancer cell invasion through the Akt/mTOR pathway." (PMID 38136676, 2023). "Zheng and colleagues showed that mTOR is inactivated by ROS, which are increased after treatment with sulforaphane (an isothiocyanate derived from cruciferous vegetables), in esophageal squamous cell carcinoma cells because of turbulence in the GSH/GSSG balance." (PMID 36082080, 2022). "In addition, GA was found to inhibit the PTEN/PI3K/AKT/mTOR pathways in esophageal squamous cell carcinoma." (PMID 35744960, 2022). "HOXD10 was found to act as a tumor suppressor, which inhibited the development of esophageal squamous cell carcinoma through the PI3K/AKT/mTOR pathway, and in another study, expression of the AKT/mTOR signaling pathway was associated with the progression of EC." (PMID 34022794, 2021). "Hsa_circ_0006168 was found to be significantly increased in the tissue and cell line level of esophageal squamous cell cancer and may regulate the expression of mTOR via sponging miRNA-100." (PMID 33292256, 2020). "Moreover, in esophageal squamous cell carcinoma (ESCC) cell lines and primary cells, the expression of PKMYT1 is associated with and regulates the activation of the AKY/mTOR pathway." (PMID 32958072, 2020). "Research has indicated that the mTOR/p70s6k signaling pathway was activated in esophageal squamous cell carcinoma and rapamycin, suppressed mTOR expression and phosphorylation of p70s6k, arrested cell cycle at the G0/G1 phase, and induced apoptosis of EC cells." (PMID 28487599, 2017). "It has been shown that in esophageal squamous cell carcinoma (ESCC), downregulated PSMD7 induces apoptosis and inhibits the aggressive behaviors of ESCC cells through the mTOR/p70S6K pathway." (PMID 35037550, 2022). "PI3K/AKT/mTOR pathway is frequently overactive in esophageal squamous cell carcinoma (ESCC), making it an attractive treatment target." (PMID 35904643, 2022). "A meta-analysis of data from 915 patients with esophageal squamous cell carcinoma (ESCC) was conducted to evaluate the prognostic and clinicopathological significance of mTOR/p-mTOR expression." (PMID 33572326, 2021). "Dysregulation of mTOR contributes to tumorigenesis, angiogenesis, cellular growth and metastasis but its roles in esophageal squamous cell carcinoma (ESCC) are controversial." (PMID 27835987, 2016).
esophageal squamous cell carcinoma (continued). "In esophageal squamous cell carcinoma, PKMYT1 promotes cellular proliferation, migration and infiltration through activation of the AKT/mTOR signaling pathway." (PMID 36747547, 2023). "Similarly, induction of esophageal squamous cell carcinoma (ESCC) autophagy through inactivation of the AKT/mTOR signaling pathway has been reported with echinatin, a compound extracted from the Chinese herb Glycyrrhiza uralensis Fisch." (PMID 36428613, 2022). "It has been established that human esophageal squamous cell carcinoma is characterized by overexpression of COX-2, iNOS, NF-κB, and mammalian target of rapamycin (mTOR)." (PMID 35630763, 2022). "miR-100 inhibits the expression of mTOR by directly targeting its 3′-UTR and acts as a tumor suppressor in esophageal squamous cell carcinoma (ESCC) and bladder cancer." (PMID 34869377, 2021). "For example, miR-382, promotes apoptosis and autophagy in esophageal squamous cell carcinoma (ESCC) by inhibiting mTOR and 4E-BP1 50, and the overexpression of miR-382 was shown to suppress the migration, invasion and epithelial-mesenchymal transition (EMT) of ESCC cells." (PMID 33390839, 2021). "Notably, in esophageal squamous cell carcinoma (ESCC), GA activates the PTEN/PI3K/AKT/mTOR pathway through the mitochondria-dependent apoptosis pathway, effectively inhibiting cancer cell proliferation while promoting apoptosis." (PMID 41311720, 2025). "Moreover, a recent study reported that UHRF1 silencing could increase the radiosensitivity of ESCC (esophageal squamous cell carcinoma) through the inhibition of the PI3K/Akt/mTOR signaling pathway." (PMID 37630248, 2023). "The prognostic impact of the PI3K/AKT/mTOR signaling pathway in advanced esophageal squamous cell carcinoma was also assessed in 145 tumor and 145 non-tumor samples of patients from China." (PMID 33572326, 2021). "In esophageal squamous cell carcinoma, ricolinostat (ACY-1215) could suppressed proliferation and promotes apoptosis via PI3K/AKT/mTOR pathway." (PMID 32332880, 2020). "Nonetheless, in both esophageal squamous cell carcinoma (ESCC) and hepatocellular carcinoma cells, MPS1 activates the AKT/mTOR pathway, promoting cell proliferation and migration." (PMID 39339232, 2024). "The same effect was described on esophageal squamous cell carcinomas (ESCC cells), metformin-induced AMPK activation and p-mTOR, S6K1 and cyclin D1 inhibition." (PMID 35327549, 2022). "However, there was evidence on correlation between phosphorylated mTOR expression and Pdpn expression in esophageal squamous cell carcinoma and traumatic brain injury, which indicated Pdpn might participated in kidney IRI via mTOR pathway, awaiting to be explored." (PMID 36970507, 2023).
cyst (103 papers, 2007 to 2026). A sac-like closed membranous structure that may be empty or contain fluid or amorphous material. "In parallel, we noted reduced expression of p-mTOR and pCREB1, implying that global proteomic changes were associated with attenuation of cyst-pathogenic signaling." (PMID 41558825, 2026). "Acute PAM treatment for one week rapidly enhanced NF-κB activation in cyst-lining epithelial cells, increased renal inflammation and cell proliferation, and was associated with activation of mTOR signaling and upregulation of c-Myc and Wnt proteins." (PMID 42123438, 2026). "Mutations in the PKD1/PKD2, which are responsible for ADPKD, affect intracellular signaling, including the mammalian target of the rapamycin (mTOR) pathway, leading to cyst formation and progression, while NF1 mutations overactivate the Ras proteins." (PMID 40051696, 2025). "This leads to a nutrient deficiency that activates AMPK and inhibits mTOR, thereby effectively reducing cyst growth." (PMID 39203719, 2024). "The ERK1/2 and mTOR/S6K pathways have been implicated in the proliferative response of cyst-lining cells." (PMID 35744960, 2022). "The second new insight from our work is that the beneficial effects of anti-miR-17 treatment are due to the regulation of multiple cyst-promoting, pathogenic pathways (mitochondrial metabolism, mTOR pathway, and inflammation)." (PMID 30760828, 2019). "Anti-miR-17 treatment recapitulated the gene expression pattern observed after miR-17~92 genetic deletion and was associated with upregulation of mitochondrial metabolism, suppression of the mTOR pathway, and inhibition of cyst-associated inflammation." (PMID 30760828, 2019). "We have shown previously that the mTOR inhibitors rapamycin and everolimus effectively reduce cyst growth and loss of renal function in an experimental animal model for PKD." (PMID 17868472, 2007). "Our results indicate that defective PCP in postnatal stages may be associated with cyst formation in mTOR-activated tubules." (PMID 36627370, 2023). "Moreover, loss of even a single AP-2β allele causes β-catenin/mTOR hyperactivation that is linked to renal fibrosis and cyst formation with age progression." (PMID 35468900, 2022). "Anti-miR-17 treatment slowed cyst growth in Pkd1flox/RC:Ksp-Cre mice, a mouse model that carries a flox allele and a R3277C mutant allele of Pkd1 gene, through regulating mitochondrial metabolism, mTOR pathway, and inflammation." (PMID 33809516, 2021). "In this sense, inhibition of glycolysis by 2-deoxyglucose, activation of AMPK, or inhibition of mTOR inhibited the Warburg effect and protected from renal function loss and cyst progression in diverse preclinical ADPKD with different speeds of progression (Figure A1)." (PMID 31336917, 2019). "Therapeutically, mTOR inhibitors like sirolimus and everolimus reduce cyst growth in animal models but have shown limited success in clinical trials, likely due to subtherapeutic kidney levels or pathway compensation." (PMID 40801635, 2025). "This increase likely results from compensatory glucose reabsorption in the proximal tubular S3 segment, potentially promoting cyst enlargement through mTOR activation and AMPK inactivation." (PMID 40214869, 2025). "The rationale is that lowering arginine availability impairs polyamine synthesis and mTOR signaling in cyst-lining cells." (PMID 40722668, 2025). "PC1 directly interacts with TSC2 and inhibits mTOR signalling, and active mTOR signalling has been found in cyst-lining cells in patients and mouse models, while mTOR inhibition reduces cysts in mice." (PMID 40722835, 2025). "For instance, in PKD, mutations in NEK8 have been linked to ciliary defects that lead to aberrant activation of pathways, such as mammalian target of rapamycin (mTOR) and Wnt, that contribute to cyst formation and growth." (PMID 41154634, 2025). "Dysfunctional GPCR signaling can disrupt this interaction, leading to unchecked mTOR activity and accelerated cyst growth." (PMID 40507782, 2025).
cyst (continued). "Abnormal GPCR signaling can hyperactivate mTOR, a key regulator of cell growth and metabolism, resulting in enhanced proliferation and cyst expansion." (PMID 40507782, 2025). "MDCK cysts have been extensively utilized to investigate signaling pathways involved in cyst expansion, including cAMP-mediated fluid secretion and mTOR activation." (PMID 40801635, 2025). "Dysfunction of ciliary GPCR signaling alters key downstream pathways, including mammalian target of rapamycin (mTOR), cyclic adenosine monophosphate (cAMP), and calcium homeostasis, exacerbating cyst formation and disease progression." (PMID 40507782, 2025). "In the Han:SPRD (cy/+) rat model of PKD, lodged calcium-phosphate microcrystals induce tubule dilation and cyst formation through the activation of the mammalian target of rapamycin (mTOR) and signal transducer and activator of transcription 3 (STAT3)." (PMID 37985930, 2024). "Bi-weekly injections with RapaMNP, rapamycin or vehicle for 6 weeks resulted in inconsistent mTOR inhibition and little change in cyst index, however." (PMID 38956234, 2024). "OPN contains an RGD domain that binds αV‐integrins, which are key mediators of mitogenic signals (such as GSK3β and mTOR) and macrophage recruitment that contribute to cyst growth." (PMID 39238069, 2024). "Evidence shows that mTOR inhibitors can effectively reduce cyst growth and preserve kidney function in ADPKD animal models of ADPKD." (PMID 39203812, 2024). "A ketogenic diet, calorie restriction, intermittent fasting, and time-restricted feeding can reduce aerobic glycolysis and inhibit the mTOR pathway, resulting in decreased cyst cell proliferation, reduced kidney volume, and preservation of kidney function." (PMID 39339816, 2024). "Management of BHD-associated cystic lung disease lacks specific therapies, and the effectiveness of mTOR inhibitors in preventing cyst formation is unclear." (PMID 39867882, 2024). "Activated AMPK can also inhibit the mammalian target of rapamycin (mTOR) pathway, which is an important driver of cyst growth when active." (PMID 38026227, 2023). "Studies have demonstrated that mTOR inhibitors can slow cyst growth, reduce kidney volume, and improve kidney function in rodent models of PKD." (PMID 37834113, 2023). "We consistently found phosphorylated S6 kinase 1 (pS6k1), a well-characterized downstream effector of mTOR, in the cyst-lining cells one week after engraftment." (PMID 35892566, 2022). "The inhibitory effects of KN-93 on mTOR signaling and cyst growth were enhanced with metformin, an AMPK activator." (PMID 36002021, 2022). "According to our data, this increase activates mTOR signaling and contributes to the proliferative drive during cyst development." (PMID 35695071, 2022). "Here, we showed that inhibition of CaMK4 and its upstream regulators, CaMKKβ and CaM, individually inhibited mTOR activity and in vitro cyst growth of the ADPKD cells." (PMID 36002021, 2022). "Recent studies have highlighted the importance of mTOR activation in cell proliferation and cyst growth in PKD." (PMID 36002021, 2022). "PF‐06409577 effectively down‐regulated mTOR pathway‐mediated proliferation of cyst‐lining epithelial cells and CFTR‐regulated cystic fluid secretion, delaying the progression of ADPKD significantly." (PMID 35748097, 2022). "AMPK activators metformin and salsalate inhibit renal mTOR activity, cell proliferation, and cyst growth in animal models of PKD; however, the clinical use of metformin for the treatment of ADPKD has not yet been demonstrated." (PMID 36002021, 2022). "The effects of metformin on AMPK activation, mTOR inhibition, and in vitro cyst formation were significantly enhanced by CaMK4 inhibition with KN-93." (PMID 36002021, 2022). "FLCN protein (folliculin) has a tumour suppressor activity interfering with the mTOR signalling pathway, a fact that provides a plausible explanation for cyst formation." (PMID 35176117, 2022).
cyst (continued). "In summary, our results reveal that ciliary cAMP signaling engages mTOR signaling to promote cell proliferation during cyst development." (PMID 35695071, 2022). "To investigate the role of CaMK4, we knocked down CaMK4 expression using shRNA and examined the effects of KN-93, a CaMK4 inhibitor, on mTOR signaling, cell proliferation, and in vitro cyst formation in human ADPKD cells." (PMID 36002021, 2022). "Rapamycin was used as a positive control in this experiment, which is recognized as an inhibitor of mTOR and is known to inhibit epithelial cell proliferation and cyst growth in a PKD mouse model." (PMID 35159293, 2022). "Reducing β-catenin hyperactivation in KCTD1 mutants through heterozygosity for the β-catenin gene Ctnnb1 attenuated mTOR hyperactivation and partially rescued the renal fibrosis and cyst formation phenotype in these mice." (PMID 35468900, 2022). "The mTOR pathway has been reported to participate in cyst growth in mammals, and inhibition of the mTOR signaling reversed the renal cystogenesis." (PMID 34545930, 2021). "ASO directed at the mTOR complex normalized the kidney function while reducing weight and cyst size in an orthologous mice model for APKD." (PMID 34944574, 2021). "Increased renal expression of the matricellular protein periostin is accompanied by upregulation of vimentin, which leads to increased mTOR activity, cell proliferation, cyst growth, interstitial fibrosis and acceleration of decline in renal function." (PMID 34206927, 2021). "An effect of fibrocystin on mammalian target of rapamycin (mTOR) activation has been found in vitro and activation of mTOR signaling has been described in cyst lining epithelium in vivo." (PMID 32847032, 2020). "Yet, metformin has been shown to activate AMPK in an ADPKD mouse model resulting in decreased cyst growth via inhibition of mTOR in vitro." (PMID 32847032, 2020). "Clinical studies have been conducted targeting cyst cell proliferation by inhibition of mTOR or transepithelial cyst secretion by pharmacological inhibition of the vasopressin 2 receptor (V2R)." (PMID 32885302, 2020). "Cystic fibrosis transmembrane conductance regulator (CFTR) is involved in cyst fluid and electrolyte secretion, and mTOR participates in the proliferation of cyst epithelial cells." (PMID 32364526, 2020). "Notwithstanding, the mTOR signaling pathway is mediated by the primary cilia and inappropriately activated in cyst-lining epithelial cells in human ADPKD patients and mouse models." (PMID 33488951, 2020). "Overall, an abundance of preclinical evidence suggests that mTOR inhibitors effectively slow cyst growth, even though the specific role of mTOR complexes is still poorly understood." (PMID 30510618, 2018). "In the lung, cyst-lining cells were suggested to be activated due to their immunostaining positivity for phospho-mTOR and phospho-S6 ribosomal protein." (PMID 29357828, 2018). "As in native cyst cells, significantly higher cAMP levels and mTOR activity were found in ciPTEC-PC1KD compared to ciPTECwt." (PMID 29632324, 2018). "Consistently, the inhibition of mTOR increases the expression levels of polycystins and slows cyst expansion." (PMID 28353628, 2017). "PI3K/mTOR-dependent aberrant growth can also affect several tissues, including kidneys, where it results in cyst formation." (PMID 28353628, 2017). "Metformin was shown to suppress cyst growth and fluid secretion through the inhibition of mTOR and CFTR in a previous study using MDCK cell cysts, mouse embryonic kidney explant cultures, and Pkd1 mouse models." (PMID 28769124, 2017). "Increased mTOR (mechanistic target of rapamycin) activity was found in cystic kidney and in particular in cyst-lining epithelium of several NPHP mouse models." (PMID 29379777, 2017).